CXCL11 (C-X-C motif chemokine ligand 11)
Diseases named in the same sentence as CXCL11 in open-access papers (continued):
Sharing a sentence is not in itself a finding about the gene and the disease.
tumor (continued). "Collectively, the results indicated that the three CTTCs (CXCL9, CXCL11, and CCL5) were selectively regulated in tumor or adjacent normal tissues and decreased with progressive stages in CRC patients." (PMID 34539647, 2021). "The result shows that in tumor cells, PMEPA1 were negatively correlated with some chemokines (including CXCL1, CXCL11, CXCL2, CXCL8, CX3CL1) and positively correlated with CXCL14 and LAG3." (PMID 34777336, 2021). "CIK cells recognize tumors mainly by chemokine ligand (CXCL) 9, CXCL10, and CXCL11, or by binding of CIK cell surface NKG2D receptor to tumor cell surface MHC class I chain-related protein A or B ligand 20,21." (PMID 33854636, 2021). "CXCL9 (p = 0.027), CXCL10 (p < 0.001), CXCL11 (p = 0.002) and CXCL13 (p < 0.001) were significantly up-regulated in tumor tissues compared with tumor-adjacent tissues, while the expression of CXCL12 (p = 0.149) was down-regulated." (PMID 34321012, 2021). "IFN-γ also enhances blood vessel maturation to promote tumor vascular remodeling and inhibit tumor growth by reducing VEGF-A levels and increasing CXCL9, CXCL10 and CXCL11 levels." (PMID 34294146, 2021). "CTTCs including CXCL9, CXCL10, CXCL11, and CCL5, which were differentially expressed between tumor and adjacent normal tissues, were significantly correlated with the abundance of several OTUs." (PMID 34539647, 2021). "We also found the upregulation of CXCL11 expression in tumor tissue compared with adjacent normal tissue in the COAD single-cell RNA-seq datasets GSE132465, and CXCL11 expression was positively correlated with PD-L1 (r = 0.78, P < 0.001)." (PMID 33777950, 2021). "This set includes tumor expression of c-Met and serum levels of HGF, IL-6, IL-8, CXCL9, CXCL10 and CXCL11." (PMID 34200459, 2021). "CXCR3 and CXCL11 have reported roles in tumor development and maintenance and ACKR3 has been proposed to scavenge excess CXCL11." (PMID 34583741, 2021). "We found that the protein expression CXCL9 (p = 0.012), CXCL10 (p = 0.003), CXCL11 (p = 0.011), CXCL13 (p = 0.004) were higher in tumor tissues than that in adjacent tissues." (PMID 34321012, 2021). "By scavenging its chemokine ligands CXCL12 and CXCL11, ACKR3 exerts important functions in embryonic development, in the regulation of leukocyte and tumor cell migration across blood vessels and in B cell immunity/activation in germinal centers." (PMID 33857173, 2021). "Our study identified that elevated CXCL11 was an independent prognostic biomarker in patients with COAD, that promoted anti-tumor immunity to prolong survival." (PMID 33777950, 2021). "CXCR7 acts on tumor progression and metastases at different levels upon interaction with endogenous ligands, including CXCL12, CXCL11 and the Macrophage Inhibitory Factor (MIF)." (PMID 33937018, 2021). "Compared to anti-PD-L1, bintrafusp alfa was also shown to increase the gene expression of molecules involved in T-cell trafficking in the tumor (e.g., CXCL11), TRAIL-mediated tumor cell lysis, and antigen-specific T-cell lysis of tumor cells." (PMID 32373533, 2020). "In this case, CXCR3+ tumor-specific T cells accumulate into tumors through interaction with CXCR3 ligands (CXCL9, CXCL10, and CXCL11)." (PMID 32292786, 2020). "Previous studies have correlated the accumulation of TILs in tumours with the expression of the chemokine receptor CXCR3 (receptor for CXCL9, CXCL10 and CXCL11)." (PMID 31803974, 2020). "While CXCR4 and CXCL12 were homogeneously expressed within tumor cells, ACKR3 was mainly identified in tumor endothelial cells but CXCL11 in pericytes." (PMID 32456359, 2020). "A difference was found between male mice with and without primary tumor differed in IL-10 and IL-16 levels, which were higher in those with tumor, and in CXCL5, CXCL11, CXCL13, CXCL16, and CCL24 levels, which were higher in those without tumor." (PMID 32545680, 2020). "CXCL9, CXCL10 and CXCL11, chemokine ligands for CXCR3, were expressed at high levels in the tumour locale." (PMID 32439888, 2020).
tumor (continued). "VV.CXCL11 demonstrated the ability to recruit total and antigen-specific T cells into the TME after CAR-T cell injection and significantly enhanced anti-tumor efficacy compared with direct delivery of CXCL11 by CAR-T cells." (PMID 32411132, 2020). "Immune cells show anti‐tumour effect against cancer cells through paracrine CXCL9, CXCL11/CXCR3 axis in tumour models." (PMID 32820615, 2020). "Meanwhile, CXCL9, CXCL10 and CXCL11, chemokine ligands for CXCR3, were expressed at high levels in the tumours, thus attracting CXCR3+CD8+ T cells." (PMID 32439888, 2020). "Treatment with CEA-TCB triggered secretion of pro-inflammatory cytokines (IFNγ, TNFα, IL-2) and several chemotactic molecules (CXCL9, CXCL10, CXCL11, CXCL13) indicating the generation of a highly inflamed tumor microenvironment." (PMID 33330050, 2020). "In addition, the observed increased expression of CXCL11 in HCC cells was linked with the upregulation of stem cell-related genes and the acquisition and maintenance of self-renewal and tumorigenic properties of tumor-initiating cells through an autocrine axis." (PMID 31216755, 2019). "We further examined the capacity of tumor cells to secrete CCL9 and CXCL11 in response to irradiation by performing in vitro and in vivo experiments." (PMID 31921127, 2019). "We found that the levels of CXCL9 and CXCL11 were significantly increased in both cell medium of irradiated EG7-OVA cells and the supernatants derived from MC38-OVA tumor tissues after irradiation." (PMID 31921127, 2019). "We also investigated the presence of CXCL12, CCL21, CXCL11, IP-10 (or CXCL10), CCL19, and CCL27, which participate to the recruitment of specific NK cell populations to the tumor site." (PMID 31105699, 2019). "In contrast, tumor suppressive mediators made up most inversely correlated genes, e.g. CXCL10, CXCL11, IL15, TNFSF10/TRAIL, and TNFSF14/LIGHT." (PMID 29141914, 2018). "Like NK cells, T cells can be mobilized, activated, and differentiated in the senescent tumor from a variety of SASP factors including CCL27, CCL2, CCL5, CXCL11, and IL-1α." (PMID 29868482, 2018). "S100P, CXCL11, and SRY (Sex Determining Region Y)-Box 11 (SOX11) display higher expression in tumor samples." (PMID 27857161, 2016). "CXCL11, also called I-TAC, a ligand for receptors CXCR3 and CXCR7, attracts CD8+ T cells and NK cells to the tumor or other inflamed sites." (PMID 26956047, 2016). "To analyze the mechanism by which MSCs-Sirt1 recruit NK cells for tumor inhibition, we measured the serum levels of chemokines CXCL9, CXCL10, and CXCL11." (PMID 27764779, 2016). "Further examination of chemokine expression revealed an enrichment of CXCL11, FGF2, IGF-1 and Shh in CD11b+Gr1+ cells isolated from spleen of LLC tumor bearing transgenic mice that lack TGFβRII only on myeloid cells (LysM+)." (PMID 25629162, 2015). "Mouse (host) microarray analysis showed a significant increase in the NK cell damage response receptor CXCR3, which binds tumor-cell specific membrane-bound activation ligands CXCL9, CXCL10, and CXCL11, all of which were also increased on the human array." (PMID 25952672, 2015). "Previous studies have found downregulation of the tumor suppressor miRNAs, miR-221, miR-222, and let-7 in PEL lines, and targeting of the T-cell attracting chemokine CXCL-11 by EBV miRNA BHRF1-3 in primary AIDS tumors." (PMID 21698185, 2011). "For the tumor stroma, a five gene classifier consisting of probesets for PSPHL (205048_s_at), CXCL10 (204533_at), CXCL11 (211122_s_at), ISG20 (204698_at), and GMDS (204875_s_at) was identified." (PMID 19225562, 2009). "Examples of those included PSPHL, TMPO, CRYBB2, and AMFR in the tumor epithelium and PSPHL, CXCL10 and CXCL11 in the tumor stroma." (PMID 19225562, 2009).
tumor (continued). "Here, we engineered an oncolytic herpes simplex virus expressing CXCL-11, IL-12 and a single-chain antibody against PD-1 (named oHSV30) to enhance CAR-T cell infiltration, cytotoxicity and persistence in the tumour microenvironment, thereby improving its therapeutic efficacy." (PMID 41935032, 2026). "We conclude that tumour-secreted CXCL10 and CXCL11 enhance CAR T cell migration." (PMID 41366257, 2025). "First, CAFs directly promote tumour proliferation and metastasis by secreting growth factors (e.g., CXCL11, CCL5): CAF-derived CCL5 enhances HCC metastasis by triggering the HIF1α/ZEB1 axis, while CXCL11 directly promotes HCC cell proliferation." (PMID 40495147, 2025). "For instance, tumour cells with high FAT2 expression have been reported to upregulate several chemokines that influence immune cell behaviour, including CCL2, CCL3, CCL4, CCL19, CXCL10, and CXCL11." (PMID 40361472, 2025). "Similarly, compared to CAF‐S4, CAF‐S5 also upregulates CCL4, CXCL9, CXCL10, CXCL11 and IL1RN suggesting that cytokine and chemokine transcripts are enriched in tumours with high CAF‐S1 and CAF‐S5 and low in the myCAF‐like subset CAF‐S4." (PMID 39743376, 2025). "Single-cell RNA sequencing of tumor samples from patients with HCC (GSE189903) revealed that intratumoral PD-L1(+) TAMs were enriched for immune-related signaling pathways and expressed chemokines including CXCL9, CXCL10, and CXCL11." (PMID 41027276, 2025). "M1 macrophages promote tumor destruction by directly killing tumor cells and by enhancing the recruitment and activation of cytotoxic CD8+ T cells and natural killer (NK) cells via secretion of CXCL9, CXCL10, and CXCL11 chemokines." (PMID 40475782, 2025). "Notably, however, our data also illustrates a strong induction of TH1‐type chemokines CXCL9, CXCL10 and CXCL11, which are ligands for CXCR3 and critical to drive T‐cell recruitment to the tumour sites." (PMID 39743376, 2025). "However, prolonged exposure to interferon-gamma transforms teammates into adversaries, producing pro-tumorigenic effects through immunosuppression (PDL1, IDO1, Fas, and FASL), angiogenesis (CXCL9, CXCL10, CXCL11, IDO1, and iNOS), and tumor cell proliferation." (PMID 39835116, 2024). "Hence, we correlated the expression level of the tumor-upregulated gene signature, comprising HAS2, MMP9, CXCL8, CXCL11, IL1B, and IL6, with the ratio of infiltrating M1 macrophages." (PMID 38329386, 2024). "IFN-γ can induce tumor cell death and trigger the release of a large number of cytokines, such as CXCL9, CXCL10, and CXCL11, thereby further recruiting NK cells and macrophages to the tumor microenvironment and inducing a non-specific anti-tumor immune response." (PMID 38534538, 2024). "It has been shown that inhibition of tumor acidosis by adenylyl cyclase inhibitor MDL-12 induces NOS, CXCL9, CXCL11, and TNF-α-expressing proinflammatory TAMs that are phenotypically similar to classical M1 macrophages, leading to suppression of tumor growth in B16 mouse melanoma." (PMID 39003350, 2024). "Moreover, in miR-29 overexpressing tumors, there were significant changes in cytokine and chemokine expression, such as upregulation of CCL5, CCL11, CXCL9, CXCL11, and CXCL16, known for their anti-tumor effects." (PMID 38890285, 2024). "Additionally, treatment of colon cancer using oncolytic herpes simplex virus (oHSV) (O-HSV1211) modified to express both IL-12 and CXCL11 leads to increased infiltration of CD8+ T and CD4+ T cells into the tumor site." (PMID 39055561, 2024). "We show here that COX2 expression at the tumor margin limits CD8+ T-cell infiltration into the tumor core, which involves at least in part reduced cytokine and chemokine expression (IRF8, CLEC9a, CXCL9, CXCL10, CXCL11, and IL27) that promotes directional immune cell migration." (PMID 39356141, 2024). "Moreover, anti-tumor chemokine genes including CXCL9, CXCL10, CXCL11 and CXCL13 expressed higher in the high-necroptosis cohort." (PMID 39247606, 2024).
tumor (continued). "CCL5, CXCL9, CXCL10, CXCL11, and CX3CL1 are involved in the recruitment of CD8+ T cells to tumours." (PMID 38291183, 2024). "Remarkably, consistent with the great immunogenicity caused by the unstable genome profiles of the HRD group, HRD tumor epithelial cells exhibited high expression of immune chemokines that recruit immune cells to mediate antitumor effects, such as CXCL8, CXCL10 and CXCL11." (PMID 39136172, 2024). "In our mouse tumor models, functional Cxcl11, the third ligand for CXCR3, is lacking in C57BL/6 mice, hence subsequent efforts will not focus on Cxcl11." (PMID 39316363, 2024). "CXCL10, CXCL5, MMP1, CXCL12, CXCL11, CXCL2, STAT1, IL‐6 and TLR2 were hub genes in network and may promote or inhibit the homing or of immune cells in tumours and immune cell differentiation, bring intratumoral immune heterogeneity." (PMID 36524848, 2023). "The results indicate that although CXCL9- and CXCL11-expressing SCCs exert anti-tumor activity, the CXCL10-expressing SCC failed to exert anti-tumor activity." (PMID 37218983, 2023). "CXCL9- and CXCL11-expressing cells showed significant anti-tumor activity, while CXCL10-expressing cells failed to exert an anti-tumor effect." (PMID 37218983, 2023). "Interferon (IFN)-inducible chemokines C-X-C motif ligand 9 (CXCL), CXCL10, and CXCL11 are anti-tumor chemokines; however, the differential anti-tumor effects of IFN-inducible chemokines are not completely understood." (PMID 37218983, 2023). "CXCL11 promotes recruitment of activated NK, CTL and Th1 cells in the tumor tissue in vivo." (PMID 37547756, 2023). "Thus, the relationship between CXCL9, CXCL10, CXCL11/CXCR3 axis and tumor development or patient prognosis is still controversial." (PMID 38264648, 2023). "CXCL10, CXCL5, MMP1, CXCL12, CXCL11, CXCL2, STAT1, IL‐6 and TLR2 were hub genes, which may drive the homing of immune cells in tumours and promote immune cell differentiation." (PMID 36524848, 2023). "The results demonstrated that although CXCL9- and CXCL11-expressing cells showed anti-tumor effects, CXCL10-expressing cells failed to exert anti-tumor effects." (PMID 37218983, 2023). "The results showed that CXCL9- and CXCL11-expressing cells markedly inhibited tumor growth, whereas CXCL10-expressing cells did not inhibit growth." (PMID 37218983, 2023). "We added rhCXCL11 and rhEGF to tumor cell with or without anlotinib treatment and found that anlotinib mediated ferroptosis effect is CXCL11 and EGFR independent." (PMID 37283515, 2023). "In addition to its influence on tumour progression through its angiostatic effects, CXCL11 is part of the CXCR7/CXCL11 axis that was shown to induce the epithelial–mesenchymal transition and metastatic behaviour of OC cells under ERα control." (PMID 37388244, 2023). "CXCL9, CXCL10, CXCL11 and CCL8 levels were positive correlated with a higher ratio between CD8+ T cells in tumor areas and the total stroma, they might affect the spatial distribution of CD8+ T cells in human pancreatic tumor tissues." (PMID 36479091, 2022). "In this context, for the first time, we found that GSK343 treatment was able to modulate the innate immune response, increasing CXCL9, CXCL10 and CXCL11 levels in GB, as a result of EZH2 inhibition, enhancing NK cell migration to tumor sites and consequently NK cell-mediated tumor growth inhibition." (PMID 36430394, 2022). "Finally, a single injection of cyclophosphamide, a drug able to induce ICD, can increase the Cxcl9, Cxcl10 and Cxcl11 expression within mastocytoma tumors (an effect dependent on CD4 T cells), thus allowing the recruitment of CD8 T cells and tumor regression." (PMID 36429101, 2022). "We found that the secretion of CXCL9, CXCL10 and CXCL11 was significantly higher in central tumor tissues compared to nontumor tissues." (PMID 35954489, 2022). "Since many tumors show increased expression of both CXCL12 and CXCL11, we now asked whether CXCL12 and CXCL11 would exert combined effects on tumor progression." (PMID 36539774, 2022).
tumor (continued). "To summarize, TDO2+ myofibroblasts were mainly located distally from tumor nests, and these cells attracted CD4+ T cells and CD8+ T cells through the CXCL9/CXCL10/CXCL11/CXCR3 axis, which may have prevented T cells from accessing tumor nests." (PMID 35972800, 2022). "In our mouse tumor models, functional CXCL11, the third ligand for CXCR3, is lacking in C57BL/6 mice." (PMID 35013216, 2022). "We conclude that CXCL12 and CXCL11 commonly have pro-apoptotic effects on tumor cells, which in most cases are absent in the simultaneous presence of the chemokines." (PMID 36539774, 2022). "In contrast to single chemokines, CXCL12 and CXCL11 in combination more potently stimulated the migration of A549 and A767 cells, but not of the other tumor cells." (PMID 36539774, 2022). "Since CXCR3 can bind to its ligands CXCL9, CXCL10, and CXCL11 to inhibit angiogenesis, CXCR3 may play an important role in wound healing and tumor growth." (PMID 36421704, 2022). "Together, these findings establish that CXCL12 and CXCL11 synergistically control migration of some, but not of all tumor cells." (PMID 36539774, 2022). "Together, our data indicate that a LINC00152/miR-205-5p/CXCL11 axis in HCC CAFs may affect the proliferation and migration of HCC cells in vitro and HCC tumor growth in vivo." (PMID 36435866, 2022). "In conclusion, our pan-cancer analyses of CXCL11 expression revealed that CXCL11 was differentially expressed in tumor and nontumoral tissues and at different tumor stages." (PMID 35935945, 2022). "We found that cisplatin-pretreated tumor cells stimulate neutrophils which expressed higher levels of cytotoxic effectors, including TNF-α, GZMB, and ELANE, and pro-inflammatory cytokines, such as CCL2, CCL3, CXCL10, CXCL11, and IL12." (PMID 35784745, 2022). "However, a high ratio of CD8+ T cells within the tumor areas in relation to the total T cells in the stroma was correlated with the secretion of CXCR3 ligands (CXCL9, CXCL10 and CXCL11) and the CCR5 ligand CCL8." (PMID 35954489, 2022). "Under the chemotactic effect of CXCL9, CXCL10, and CXCL11, activated Th1 cells reach the tumor site to exert phagocytosis and upregulate CXCL9, CXCL10, and CXCL11 secretion, thus recruiting more T lymphocytes to participate in the immune response at the lesion site." (PMID 36479091, 2022). "We found that when neutrophils were co-cultured with cisplatin-pretreated tumor cells, they expressed significantly higher levels of chemokines, such as CXCL9, CXCL10, and CXCL11, which could be key regulators of recruitment of T cells into tumor tissues." (PMID 35784745, 2022). "Furthermore, the expression levels of CXCL9, CXCL10, CXCL11, and their receptor CXCR3, which perform anti-tumor roles in ICI treatment, were found to have increased in PTPRD/PTPRT mutant cancer patients." (PMID 36248841, 2022). "We analyzed the CXCL11 differential expression in tumor tissue and nontumoral tissue and in different stages of cancers." (PMID 35935945, 2022). "In addition to their direct effects on tumor cell function, CXCL12 and CXCL11 indirectly control tumor progression by modulating the tumor microenvironment, thereby affecting immune responses and tumor angiogenesis." (PMID 36539774, 2022). "As for the genes regulated by EBV-miRNAs, the CXCL9, CXCL10, CXCL11/CXCR3 axis has been found to regulate immune cell migration, differentiation, leading to tumor suppression and may have potential role in cancer treatment." (PMID 36544484, 2022). "To assess the involvement of these signaling molecules in chemokine-induced migration of the various tumor cells, we tested CXCL12- and CXCL11-dependent chemotactic responses in the presence of the Erk inhibitor, PD98059, the PI-3 K inhibitor, Ly294002, and the p38 inhibitor, SB203580." (PMID 36539774, 2022). "To determine whether CYLD exerts a similar effect on tumor-intrinsic chemokine production as SPATA2, we transiently knocked down CYLD by RNAi and measured CXCL9, CXCL10, and CXCL11 secretion." (PMID 36531014, 2022).